CR1 (complement C3b/C4b receptor 1 (Knops blood group))
Diseases named in the same sentence as CR1 in open-access papers (continued):
Sharing a sentence is not in itself a finding about the gene and the disease.
breast carcinoma (7 papers, 1994 to 2024). "Previous research suggests that CR-1 is overexpressed in several types of human cancers such as gastric cancer, glioblastoma, bladder cancer, breast cancer, hepatocellular carcinoma, lung cancer and esophageal squamous cell carcinoma." (PMID 31455359, 2019). "The functions of CR-1 in stimulating proliferation and survival of endothelial cells have been proven in a breast cancer model." (PMID 31455359, 2019). "Together, our findings suggest that CR1 has the potential to regulate CD44 expression in breast cancer and BCSCs via its interaction with AP-1 and NFκB factors." (PMID 23226410, 2012). "Our further analysis was thus focused on the activities of CR1 in regulating gene expression in breast cancer cells." (PMID 23226410, 2012). "Consistent with the notion that there was a difference in trans-acting factor(s) binding to CR1, mutations of TFBSs for AP-1and NFκB resulted in a significant reduction in GFP expression in two breast cancer cell lines." (PMID 23226410, 2012). "In other human malignancies, with the possible exception of breast cancer, it is still unclear as to whether CR-1 may have prognostic significance." (PMID 25596738, 2015). "In addition, overexpression of CR-1 increases the invasiveness and the resistance to anoikis of human breast cancer cells." (PMID 21863025, 2011). "The CR1 and CR3 levels observed for serum from normal female donors versus serum from breast cancer patients were represented with an n = 10 for both groups (D respectively)." (PMID 39518018, 2024). "Using the same immune reagent, human breast cancer cell lines and tumor tissue were stained positive for CR1, while adjacent non-involved tissue was negative." (PMID 39518018, 2024). "The inability to completely eliminate CR1 expression implies other TFs and/or co-factors may be involved in regulating CD44 expression in breast cancer stem-like SUM 159 cells." (PMID 23226410, 2012). "Genomic sequencing of CR1 from breast cancer cell lines did not reveal any major mutations that cause changes in key TFBSs, which suggests that variations in reporter gene expression among these cells may be attributed to the difference in trans-acting factor binding to CR1." (PMID 23226410, 2012). "To characterise the role of CR-1 in human melanoma, we screened 21 human melanoma cell lines for expression of CR-1 transcripts by real-time PCR and using as calibrator the SK-Br-3 breast cancer cell line that shows relatively low levels of CR-1 mRNA." (PMID 21863025, 2011). "In addition, antisense nucleic acid technique on CR-1, and antagonist of the CR-1 CFC domain have been reported to inhibit human breast cancer, colon cancer and testicular cancer cells growth, suggesting that CR-1 is a valuable therapeutic target for targeting CSLCs in ESCC." (PMID 28431580, 2017).
cerebral malaria (7 papers, 2012 to 2023). A sequestration of Plasmodium falciparum in the brain, which can cause coma and/or seizures. "The CR1 risk variant, rs17047661, gives rise to the Sl1/Sl2 (R1601G) allele that was previously associated with protection against cerebral malaria." (PMID 38076851, 2023). "One of the SNPs in the promoter, rs9429942 (T allele), was reported to be associated with high expression of erythrocyte CR1 as well as protection against cerebral malaria in Thai populations." (PMID 36626386, 2023). "Another study on the Thai population found that a variant in the CR1 promoter which is related to high expression levels of the gene was associated with protection against cerebral malaria." (PMID 36626386, 2023). "The expression of CR1 contributes to the rosetting of erythrocytes in the brain bloodstream, causing cerebral malaria, the most severe form of the disease." (PMID 36626386, 2023). "Recently, two distinct CR1 polymorphisms commonly seen in African populations were found to demonstrate opposing correlation with the development of cerebral malaria in Kenya." (PMID 31316507, 2019). "Another polymorphism that increases RBC surface expression of CR1 was reported to confer protection against cerebral malaria development in Thai population." (PMID 31316507, 2019). "In conclusion, we show that two high frequency CR1 polymorphisms have opposing associations with cerebral malaria and death in Kenyan children." (PMID 29690995, 2018). "Two neighboring CR1 polymorphisms belonging to the Knops blood group system of antigens had opposing associations on risk of cerebral malaria." (PMID 29690995, 2018). "The CR1 low expression genotype (TT) has been shown to be associated with protection against cerebral malaria in an eastern Indian cohort." (PMID 23152904, 2012). "Future studies showing how the CR1 mutation protects against cerebral malaria could help identify new treatments that prevent severe disease or death." (PMID 29690995, 2018). "Therefore, similar to HbC, blood group O and RBC CR1 deficiency, it is possible that reduced rosetting and subsequent reduced microvascular obstruction may in part explain the protective association of Sl2 against cerebral malaria." (PMID 29690995, 2018). "The data presented here provide epidemiological evidence supporting a role for CR1 in the pathogenesis of cerebral malaria." (PMID 29690995, 2018). "A new polymorphism in the promoter region of the CR1 gene (rs9429942) was associated with higher levels of CR1 on the surface of RBC and protection against cerebral malaria in Thailand." (PMID 23316245, 2012).
lung carcinoma (7 papers, 2014 to 2023). "The potential interaction between SNP (rs7525160 G > C) of CR1 and smoking status suggested that CR1 rs7525160 G > C was significantly related to an increased risk of lung cancer." (PMID 37342563, 2023). "In lung cancer, few studies reported the association between CR‐1 expression and poor prognosis in early NSCLC patients." (PMID 37528674, 2023). "Although serum CR‐1 is a potentially useful auxiliary diagnostic or prognostic marker, it is insufficient as a single diagnostic marker for lung cancer." (PMID 35949510, 2022). "Previous studies have shown that overexpression of CR‐1 in lung cancer is associated with poor prognosis." (PMID 35949510, 2022). "CR‐1 is overexpressed in lung cancer tissues, and the level of CR‐1 expression is associated with the prognosis." (PMID 32697011, 2020). "We found that the CR‐1 was overexpressed in lung cancer and that this overexpression was associated with a worse outcome for stage I NSCLC patients." (PMID 32697011, 2020). "We conducted a case-control study in Chinese subjects and found an intronic SNP (rs7525160 G > C) of CR1 was significantly associated with lung cancer risk." (PMID 24621201, 2014). "Given the involvement of the complement system in coordinating innate immunity and inflammatory response, further examination of the potential association between genetic variation of CR1 genes and lung cancer is warranted." (PMID 24621201, 2014). "However, the association of genetic variants of CR1 with susceptibility to lung cancer remains unexplored." (PMID 24621201, 2014). "Genetic variant of CR1 could alter gene function and result in deregulation of the inflammatory and immune responses, thereby, modulating the susceptibility to lung cancer." (PMID 24621201, 2014). "Thus, it is likely that the genetic variants of CR1 in the complement system confer the susceptibility to lung cancer." (PMID 24621201, 2014). "In our study, the association of CR1 polymorphism with lung cancer is biologically plausible in that the intronic polymorphism could affect the density of CR1 molecules on the cell surface, thereby contributing to autoimmune disorders and neoplasm." (PMID 24621201, 2014). "However, the association of genetic variants of CR1 with risk of lung cancer remains unexplored." (PMID 24621201, 2014). "However, whether the genetic variants of CR1 are related to the risk of lung cancer remains unknown." (PMID 24621201, 2014). "We aim to explore the expression of Cripto‐1 (CR‐1) protein in patients with early stage non‐small cell lung cancer (NSCLC)." (PMID 37528674, 2023). "CR‐1 protein was highly expressed in lung cancer tissue and serum, and its expression level is related to prognosis." (PMID 35949510, 2022). "The serum levels of CR‐1 have been proved prognostic value in several tumours, such as colon cancer and lung cancer." (PMID 32697011, 2020). "It has been reported that there is a positive correlation between high levels of CR‐1 in serum and metastasis development in lung cancer patients." (PMID 32697011, 2020). "The purpose of this study was to investigate the significance of CR‐1 expression in surgically resected stage I non‐small cell lung cancer (NSCLC)." (PMID 32697011, 2020). "Evidence also suggests that the level of CR-1 is elevated in the circulating serum of patients with lung cancer, hepatocellular carcinoma, breast and colon carcinomas." (PMID 31455359, 2019). "Recently, our studies showed that serum CR‐1 might be a potential biomarker for lung cancer diagnosis." (PMID 32697011, 2020). "In addition, it was found that CR‐1 was overexpressed in lung tumours, and its high expression was related to lymph node metastasis and advanced disease stage, indicating its important role in lung cancer progression and metastasis." (PMID 37528674, 2023). "Recent studies suggest that serum CR‐1 may be a biomarker for the diagnosis of lung cancer." (PMID 37528674, 2023).
lung carcinoma (continued). "However, few studies have assessed the clinical significance of serum CR‐1 levels in lung cancer." (PMID 35949510, 2022). "In this study, the levels of CR‐1 and VEGF in peripheral blood of lung cancer were determined by ELISA, and the relationship between the CR‐1 and VEGF and clinical significance was evaluated." (PMID 35949510, 2022). "The main aim of our study was to investigate the clinical value of CR‐1 and VEGF for non‐small cell lung cancer (NSCLC) patients." (PMID 35949510, 2022). "In conclusion, CR‐1 is a prognostic factor in stage I NSCLC patients, and may be related to lung cancer distant metastasis." (PMID 32697011, 2020).
rheumatoid arthritis (7 papers, 2011 to 2025). A chronic, systemic autoimmune disorder characterized by inflammation in the synovial membranes and articular surfaces. "A previous study investigated genetic variants affecting erythrocyte sedimentation rate (ESR) in patients with severe active rheumatoid arthritis (RA) and found that the CR1 rs6691117 genotype showed a significant association with baseline ESR levels (P = 0.01)." (PMID 41346622, 2025).
sarcoma (7 papers, 2011 to 2025). A usually aggressive malignant neoplasm of the soft tissue or bone. "FDC sarcomas generally present the immunophenotype of normal FDCs, being positive for: CD21 (CR2), CD23 (Fc epsilon RII) and CD35 (CR1)." (PMID 33520702, 2020).
colon carcinoma (6 papers, 2015 to 2022). "AQP1, a Colton blood group antigen system gene, was reported to be associated with poor prognosis in colon cancer and lung adenocarcinoma, while seven of the fifteen genes were reported to be prognostic in one tumor type (GCNT2, FUT7, FUT3, FUT2, DARC, CR1 and BSG)." (PMID 35955933, 2022). "The truncated form of CR-1 is implicated in human colon carcinomas and hepatic metastases of colon carcinoma, but its function in HCC has not yet been elucidated." (PMID 34517344, 2021). "Previous studies showed that NT2/D1 cells and four different human embryonal carcinoma cell lines expressed only the FL-CR-1 transcript, whereas, human colon carcinoma and hepatocarcinoma cell lines (SW480, SW620, LS174T, GEO, CBS, HepG2 and Hep3B) expressed only the truncated form of CR-1 mRNA." (PMID 34517344, 2021). "Since the short form of CR-1 is the major transcript in HCC and colon cancer cells, we hypothesize that it may be involved in cancer progression." (PMID 34517344, 2021).
hepatocellular carcinoma (6 papers, 2019 to 2026). A malignant tumor that arises from hepatocytes. "In this study, we investigated the role of embryonic gene Cripto-1 (CR-1) in hepatocellular carcinoma (HCC) using hepatocyte-specific CR-1-overexpressing transgenic mice." (PMID 34517344, 2021). "In hepatocellular carcinoma (HCC) cells, CR-1 binds and stabilizes DVL3, helped by the concomitant binding of the Frizzled receptor FZD7 and the transmembrane lipoprotein LRP6, resulting in a more sustained signal from the Wnt/β-catenin axis." (PMID 34360603, 2021).
sarcoidosis (6 papers, 2023 to 2025). Sarcoidosis is a multisystemic disorder of unknown cause characterized by the formation of immune granulomas in involved organs. "The CR1 gene was previously connected to uveitis associated with sarcoidosis due to a gene polymorphism thought to affect disease susceptibility, implicating a genetic predisposition." (PMID 40270958, 2025). "Enriched genes including MPO (myeloperoxidase), CXCL11, IL1A, CXCL10, FCGR3B, IL1B, TTN (titin), BATF2, VIP (vasoactive intestinal peptide), TLR3, CCR2, TLR7, and CR1 wereclosely related to sarcoidosis." (PMID 38137330, 2023). "As we have previously shown, in the blood of patients with sarcoidosis, there is an overrepresentation of monocytes possessing all three classical classes of Fcγ receptors (FcγRI—CD64, FcγRII—CD32, and FcγRIII—CD16) and a decrease of these cells with CR1 (CD35) and CR4 (CD11c)." (PMID 37298666, 2023).
amyloid (5 papers, 2018 to 2023). "In lobar ICH, variants on the CR1 gene were found to influence the severity of amyloid deposition and amyloid related ICH." (PMID 37168667, 2023). "It has been suggested that the CR1*2 variant is associated with lower CR1 expression on erythrocytes, reducing the efficiency of peripheral immune complex handling and impacting amyloid clearance from the brain." (PMID 33804666, 2021). "CR1 (Complement receptor 1) and its network appears to be involved in these same phenotypes and was previously implicated in AD and amyloidosis." (PMID 33946285, 2021). "The involvement of CR1 in the pathogenesis of AD might be linked to insufficient clearance of amyloid deposits." (PMID 30044434, 2018). "Moreover, CR1 is a necessary component of complement system, and it has been reported to have a close connection with amyloid plaque burden during aging." (PMID 32919460, 2020).
glomerulopathies (5 papers, 2009 to 2023). "Previous studies have shown reduced CR1 in injured podocytes from patients with different types of glomerulopathies and one study also showed reduced CR1 expression in lupus nephritis." (PMID 28814945, 2017). "It has been shown that CR1 can be found in the urine of both healthy subjects and patients afflicted by glomerulopathies, but more work must be done in order to understand the expression of urinary CR1 in individual glomerular disease states." (PMID 24327929, 2013). "Previous studies showed that synthesis of membrane-bound CR1 on the podocytes is reduced in patients with advanced glomerular disease." (PMID 22111871, 2011). "Decreased expression of SYN, CR1 and NEP on podocytes has been found in a variety of glomerular diseases." (PMID 23675111, 2009).
leiomyosarcoma (5 papers, 2011 to 2023). An uncommon, aggressive malignant smooth muscle neoplasm, usually occurring in post-menopausal women. "CR-1 is not usually expressed in adult normal tissues, whereas high expression of CR-1 transcript and/or protein has been observed in different human carcinomas, including breast, colon, stomach, pancreas, lung, ovary, cervix and testis, and in leiomyosarcomas of the uterus." (PMID 21863025, 2011).
lymphoma (5 papers, 2015 to 2025). A malignant (clonal) proliferation of B- lymphocytes or T- lymphocytes which involves the lymph nodes, bone marrow and/or extranodal sites. "We have also described the presence of LoF variants in the genes CR1, IBTK, and NCOR2 that have been related to B cell development and activation, agammaglobulinemia, and lymphoma, respectively." (PMID 29867916, 2018). "We also find that CMLD011580 can synergize with the DNA damaging agent, doxorubicin against Myr-Akt/Eμ-Myc lymphomas in vivo, despite the apparent inhibition of translation exerted by CMDL011580 in vivo being significantly shorter than (−)-CR-1-31-b." (PMID 30718665, 2019).